ITM2A (integral membrane protein 2A)
Diseases named in the same sentence as ITM2A in open-access papers (continued):
Sharing a sentence is not in itself a finding about the gene and the disease.
cervical cancer (6 papers, 2020 to 2025). A primary or metastatic malignant neoplasm involving the cervix. "In accordance with our results, the low expression of ITM2A in breast, ovarian, and cervical cancer tissues has been associated with poorer prognosis and advanced tumor stage." (PMID 40867248, 2025). "This study aims to detect the expression of ITM2A in cervical cancer tissues and cells with cisplatin treatment, and the underlying mechanism of ITM2A in cisplatin resistance of cervical carcinoma." (PMID 34872446, 2021). "In summary, we demonstrated that ITM2A is downregulated and associated with poor survival in cervical cancer with chemotherapeutic relapse." (PMID 34872446, 2021). "Different expression levels of ITM2A were also associated with the specific histological phenotype of cervical cancer." (PMID 32300605, 2020). "Our study constructed a prognostic model in cervical cancer and discovered two novel genes, ITM2A and DSG2, associated with cervical carcinogenesis and survival." (PMID 32300605, 2020). "ITM2A expression was associated with the histology of cervical cancer." (PMID 32300605, 2020). "In addition, low expression of ITM2A is associated with poor survival in cervical cancer patients." (PMID 34872446, 2021). "The expression of ITM2A was significantly downregulated in cisplatin-resistant cervical cancer cells." (PMID 34872446, 2021). "The expression of ITM2A was decreased in tumor tissues of cervical cancer with cisplatin treatment compared with normal tissues." (PMID 34872446, 2021). "Then, we collected 40 cases of cervical cancer relapse specimen from patients treated with cisplatin and measured ITM2A protein using IHC staining." (PMID 34872446, 2021). "To clarify the function of ITM2A in cervical cancer, we also analyzed the expression of ITM2A in cisplatin-resistant cervical cancer cell lines." (PMID 34872446, 2021). "Here, we used bioinformatics analysis to screen out ITM2A, a decreased DEGs in cervical cancer with chemotherapy relapse." (PMID 34872446, 2021). "Collectively, these data indicated that the expression of ITM2A is downregulated in cervical cancer after cisplatin treatment." (PMID 34872446, 2021). "Mechanically, ITM2A upregulation mediates the sensitivity of cervical cancer cell through Notch signaling pathway." (PMID 34872446, 2021). "The results showed that the expression of ITM2A was significantly downregulated in cervical cancer tissue specimens and cells resistant to cisplatin chemotherapy." (PMID 34872446, 2021). "Our results indicated that ITM2A negatively regulates cisplatin resistance in cervical cancer through Notch signal pathway." (PMID 34872446, 2021). "ITM2A has the potential to serve as a new marker in the release of drug resistance in the future treatment of cervical cancer." (PMID 34872446, 2021). "In this study, we demonstrated that ITM2A is a decreased DEGs in cervical cancer patients with chemotherapeutic relapse." (PMID 34872446, 2021). "We chose the key gene-ITM2A of DEGs from TCGA by bioinformatics analysis, and then we analyzed the expression of ITM2A in cervical cancer cells and tissues." (PMID 34872446, 2021). "The expression of ITM2A was significantly downregulated in patients with recurrent cervical cancer after clinical cisplatin treatment." (PMID 34872446, 2021). "In this study, we demonstrate that ITM2A positively regulated the sensitivity of cisplatin in cervical cancer cells." (PMID 34872446, 2021). "Cervical cancer patients with a low expression of ITM2A were more likely have adenocarcinoma or adenosquamous carcinoma, while cervical cancer patients with a high expression of ITM2A tended have squamous carcinoma." (PMID 32300605, 2020). "In cervical cancer, ITM2A can be used as a predictive marker for overall survival prognosis." (PMID 39720726, 2024). "Next, we analyzed the mRNA expression of ITM2A in cervical cancer from TCGA database." (PMID 34872446, 2021).
cervical cancer (continued). "However, the molecular mechanisms of ITM2A in regulation of the drug resistance in cervical cancer need further research." (PMID 34872446, 2021). "Here, we obtain similar results for ITM2A in autophagy regulation in cervical cancer cells." (PMID 34872446, 2021). "Overexpression of ITM2A increases the cisplatin sensitivity of cervical cancer cells." (PMID 34872446, 2021). "Overexpression of ITM2A increases the sensitivity of cervical cancer to cisplatin." (PMID 34872446, 2021). "In addition, ITM2A negatively regulates the sensitivity of cisplatin in cervical cancer cells through Notch signaling pathway." (PMID 34872446, 2021). "Our study suggests that ITM2A may serve as a target in mediating cisplatin-resistant cervical cancer." (PMID 34872446, 2021). "Moreover, ITM2A is further downregulated in cisplatin-resistant cervical cancer cells SIHA and Hela." (PMID 34872446, 2021). "Moreover, ITM2A negatively regulates the cisplatin sensitivity of cervical cancer cells and inhibits colony formation in cervical cancer cells." (PMID 34872446, 2021). "The expression of ITM2A is reduced in cervical cancer cells with cisplatin resistance." (PMID 34872446, 2021). "In this study, ITM2A was shown to be downregulated and related to good outcomes in cervical cancer." (PMID 32300605, 2020). "In clinical practice, ITM2A might be used as an indicator for the classification of cervical cancer, and cervical cancer patients with low ITM2A expression could be treated more aggressively." (PMID 32300605, 2020). "Cervical cancer patients with a low expression of ITM2A were more likely to have adenocarcinoma or adenosquamous carcinoma, while cervical cancer patients with a high expression of ITM2A tended to have squamous carcinoma." (PMID 32300605, 2020). "Furthermore, ITM2A is also downregulated in cervical cancer cells with cisplatin resistance." (PMID 34872446, 2021). "We speculated that ITM2A may also play a critical role in drug resistance of cervical cancer." (PMID 34872446, 2021). "Furthermore, ITM2A was related to different histological phenotypes of cervical cancer." (PMID 32300605, 2020). "However, the function of ITM2A in drug resistance in cervical cancer remains unclear." (PMID 34872446, 2021). "Therefore, ITM2A may also exert an important role in cervical cancer development and treatment." (PMID 34872446, 2021). "The overexpression of ITM2A, ATP2A3, and tumor suppressor gene SFRP1 is also closely related to a better prognosis of cervical cancer." (PMID 34030694, 2021). "However, the function and mechanism of ITM2A in drug resistance in cervical cancer has not been completely clarified." (PMID 34872446, 2021). "However, there has been no paper about the expression and prognostic value of ITM2A in cervical cancer." (PMID 32300605, 2020). "It is worth noting that ITM2A and DSG2 are two novel genes that have never been studied in cervical cancer." (PMID 32300605, 2020).
hepatocellular carcinoma (3 papers, 2020 to 2024). A malignant tumor that arises from hepatocytes. "ITM2A was associated with the process of iron apoptosis in hepatocellular carcinoma and involved in the regulation of the immune system." (PMID 39720726, 2024). "We found that ITM2A, LTB, TNFRSF4, and TNFRSF18 were significantly overexpressed in hepatocellular carcinoma cell lines (Hep3B and Huh7) relative to normal liver cell lines (HL-7702)." (PMID 37006257, 2023).
acute myeloid leukemia (2 papers, 2018 to 2020). Acute myeloid leukemia (AML) is a group of neoplasms arising from precursor cells committed to the myeloid cell-line differentiation. "Some of these genes have already been shown to play a role in hematologic malignancies, including CLL (Pim-2, Met, Rgs16, Ccdc88a, Zcchc18, Clip3), diffuse large B cell lymphoma, follicular lymphoma (Vav3), acute lymphoblastic leukemia (ALL) (Itm2a, Chst1) or acute myeloid leukemia (AML) (Chd3)." (PMID 30271400, 2018).
autoimmune thyroid disease (2 papers, 2020 to 2023). Inflammatory disease of the thyroid gland due to autoimmune responses leading to lymphocytic infiltration of the gland. "we found that ITM2A rs1751094 CC was disease‐susceptible and rs1751094 AA was disease‐protective genotypes in autoimmune thyroid disease (AITD) patient groups." (PMID 36988246, 2023). "In a study of 166 pediatric patients with autoimmune thyroid disease (AITD), the ITM2A rs1751094 single‐nucleotide polymorphism (SNP) was genotyped." (PMID 36988246, 2023). "Autoimmune thyroid disease (AITD) manifests with a female predominance, and much attention has been directed towards the integral membrane protein 2 A (ITM2A) gene located on the X chromosome." (PMID 36988246, 2023).
bladder cancer (2 papers, 2024 to 2025). "A recent study underscored a significant correlation between low ITM2A expression in bladder cancer tissues and high tumor grade, pathological stage, and poor overall survival." (PMID 40867248, 2025). "In bladder cancer, ITM2A inhibits bladder cancer by downregulating STAT3 phosphorylation." (PMID 39720726, 2024).
cervical adenocarcinoma (2 papers, 2020 to 2021). An adenocarcinoma arising from the cervical epithelium. "Our study found that the low expression of ITM2A was associated with poor prognosis and cervical adenocarcinoma." (PMID 32300605, 2020). "In addition, our study also found that the low expression of ITM2A was associated with cervical adenocarcinoma." (PMID 32300605, 2020). "Moreover, the low expression of ITM2A was associated with cervical adenocarcinoma." (PMID 34872446, 2021).
triple-negative breast carcinoma (2 papers, 2023 to 2025). An invasive breast carcinoma which is negative for expression of estrogen receptor (ER), progesterone receptor (PR), and human epidermal growth factor receptor 2 (HER2). "Subsequent investigation was directed towards elucidating the function of ITM2A in influencing the prognosis of patients diagnosed with triple-negative breast cancer." (PMID 40657365, 2025). "The ensuing analyses yielded findings that suggest ITM2A as a promising therapeutic target for triple-negative breast cancer, with potential implications in both immune-related and prognostic-related contexts, as well as in the context of copper-death-related processes." (PMID 40657365, 2025).
adenoma (1 paper, 2023). A neoplasm arising from the epithelium. "The genes CA2, CA7, and ITM2C collectively play critical roles in CRC progression, with CA2 influencing adenoma characteristics and cell proliferation, CA7 acting as a tumor suppressor gene, and ITM2C likely sharing similar tumor-suppressive properties with its family member ITM2A." (PMID 37895185, 2023).
Arthritis (1 paper, 2024). Inflammation of a joint. "Genes commonly associated with T cell activation, such as LAG3, CCL5, ITM2A, CCR5, and CD2, were highly expressed in SF, in comparison to PB T cells of arthritis patients." (PMID 38254179, 2024).
autoimmune disease (1 paper, 2023). A disorder resulting from loss of function or tissue destruction of an organ or multiple organs, arising from humoral or cellular immune responses of the individual to their own tissue constituents. "ITM2A has been identified as playing a role in autoimmune disease and myogenic differentiation." (PMID 36988246, 2023).
Bell's palsy (1 paper, 2025). Partial or complete paralysis of the facial muscles of one side of a person's face. "Our results of the analyses suggest that HMOX2, DEFB128, DDX58 and ITM2A may act as risk factors for Bell’s palsy, but their association with the JAK/STAT signaling pathway is weak." (PMID 40299566, 2025). "In this study, 70 inflammation-related proteins that may be causally associated with Bell’s palsy were identified by MR analysis, and 7 significantly related proteins were screened by external dataset validation, including BLVRB, HMOX2, TNFRSF12A, DEFB128, ITM2A, DDX58 and VEGF-A." (PMID 40299566, 2025).
cervical tumor (1 paper, 2021). "ITM2A is downregulated in cervical tumor tissues and is associated with poor survival." (PMID 34872446, 2021).
chronic pancreatitis (1 paper, 2022). A chronic inflammatory process causing damage and fibrosis of the pancreatic parenchyma. "In addition, psupertime suggests candidates for further study: ITM2A has the highest absolute gene coefficient and is highly differentially regulated in a model of chronic pancreatitis, but has not been investigated in acinar cells." (PMID 35758781, 2022).
colorectal cancer (1 paper, 2023). A primary or metastatic malignant neoplasm that affects the colon or rectum. "It was observed that high expression levels of ITM2A are associated with more prolonged overall survival and relapse-free survival in patients with colorectal cancer." (PMID 37895185, 2023).
emphysema (1 paper, 2023). "This included different directions of effect among one variant for lung function near ITM2A and four variants for emphysema near TAB3, TBX22, GUCY2F, and FMR1-AS1." (PMID 36726148, 2023).
fibrosarcoma (1 paper, 2007). A malignant mesenchymal fibroblastic neoplasm affecting the soft tissue and bone. "Golub-score analysis identified a relatively poor discriminatory signal of 200 genes for the fibrosarcomas, which regardless of high FDR contained several of the upregulated genes previously associated with fibrosarcoma, e.g. BMI1, H1F0, LEF1, RBM4, ITM2A, IGFBP2 and PTGS2." (PMID 17359542, 2007).
leukemia (1 paper, 2017). A malignant (clonal) hematologic disorder, involving hematopoietic stem cells and characterized by the presence of primitive or atypical myeloid or lymphoid cells in the bone marrow and the blood. "Additionally, we also picked some of the strong candidates (e.g., ITM2A) for analyses with shRNA system in other leukemia cell lines for validation." (PMID 28415601, 2017).
Obesity (1 paper, 2025). Accumulation of substantial excess body fat. "To validate these findings, we performed immunohistochemical staining for ITM2A in sWAT from lean donors and patients with obesity." (PMID 40562785, 2025). "ITM2A expression was significantly reduced in sWAT from patients with obesity compared to lean sWAT." (PMID 40562785, 2025). "Additionally, we also detected ITM2A+ ECs in human vWAT, which are also reduced in vWAT from patients with obesity." (PMID 40562785, 2025).
pancreatic cancer (1 paper, 2020). "Even though we focused on CCDC80 in the present study, it would be worth investigating whether ITM2A and SFRP1 are involved in the action of combination treatment of vactosertib with nal-IRI/5-FU/LV in ameliorating pancreatic cancer." (PMID 32076068, 2020).
prostate adenocarcinoma (1 paper, 2024). "Supporting that contention is that ITM2A gene transcripts were also shown to be downregulated in human prostate adenocarcinoma patients compared to control subjects." (PMID 39766038, 2024). "In prostate adenocarcinoma tissue, ITM2A expression was also shown to be downregulated relative to a normal prostate." (PMID 39766038, 2024). "Analysis of the TCGA dataset, using the UALCAN analysis platform, also revealed a significant downregulation of ITM2A gene transcripts in human prostate adenocarcinoma patients compared to control subjects." (PMID 39766038, 2024).
prostate tumor (1 paper, 2024). "CXCR1 expression, not CXCR2, upregulates the tumor suppressor ITM2A to inhibit prostate tumor growth." (PMID 39766038, 2024).
sarcoma (1 paper, 2014). A usually aggressive malignant neoplasm of the soft tissue or bone. "In the murine thymoma cell line, EL4, the Itm2a protein was observed in large cytoplasmic vesicles, and then translocated to the plasma membrane in the activated cells, whereas Itm2a protein was detected in the nuclei of human uterine endometrial stromal sarcoma cells." (PMID 25079563, 2014).
schizophrenia (1 paper, 2025). A major psychotic disorder characterized by abnormalities in the perception or expression of reality. "Using an integrative approach combining bulk transcriptomics, snRNA-seq, and an MK-801 mouse model, we observed reduced OXPHOS in schizophrenia and identified three candidate genes—MALAT1, PPIL3, and ITM2A—associated with this process." (PMID 41199749, 2025). "To probe its molecular basis in schizophrenia, we applied complementary methodologies with multi-level validation, which converged on three genes—MALAT1, PPIL3, and ITM2A—that consistently correlated with OXPHOS activity." (PMID 41199749, 2025). "ROC analysis showed that five genes—MALAT1, PPIL3, ITM2A, MTA2, and GJA1—effectively distinguished schizophrenia from controls (AUC >0.70)." (PMID 41199749, 2025). "Correlation analysis linked OXPHOS scores positively with PPIL3 and ITM2A, negatively with MALAT1 and GJA1, and not significantly with MTA2, suggesting their role in schizophrenia-related mitochondrial dysfunction." (PMID 41199749, 2025).
T-cell lymphoma (1 paper, 2020). "ITM2A is GATA3-related gene and has been reported as a downstream target in T-cell lymphoma." (PMID 32631357, 2020).
viral infection (1 paper, 2021). "Increased expression was also observed for the cell-surface phagocytosis receptor, Fcgr3a, and genes linked to autophagy (Atg12, Snx4), antigen presentation pathway (RT1-CE6), Itm2a, involved in immunoglobulin production, and Oas1g, an immune response protein against viral infection." (PMID 34587117, 2021).